RNU7-37P (RNA, U7 small nuclear 37 pseudogene)
Synonyms: U7.37; HSU7.732A; RNU7P1; U7; U7.68; RNU7-68P
Gene: Small nuclear RNA gene on chromosome X (120,503,037 to 120,503,096, reverse strand). Ensembl gene ENSG00000251707.
Homologues: Orthologues: chimpanzee U7 (100% identical), macaque U7 (97% identical). Paralogues in human: RNU7-40P (90% identical), RNU7-70P (90% identical), RNU7-1 (88% identical), RNU7-123P (88% identical), RNU7-130P (88% identical), RNU7-14P (88% identical), RNU7-19P (88% identical), RNU7-20P (88% identical), RNU7-48P (88% identical), RNU7-61P (88% identical), RNU7-73P (88% identical), RNU7-7P (88% identical), and 142 more.